ENSG00000284684 (novel protein)
Synonyms: LOC128125818
Gene: Protein-coding gene on chromosome 4 (6,064,977 to 6,070,162, reverse strand). Ensembl gene ENSG00000284684.
Genetic constraint (gnomAD): Loss-of-function variants: 0 observed, 2.21 expected, observed/expected ratio (o/e) 0, 90% interval 0 to 1.26. That is too few expected variants to judge how well the gene tolerates losing a copy. Missense variants: 14 observed, 12.07 expected, observed/expected ratio (o/e) 1.16, 90% interval 0.76 to 1.75. Synonymous variants: 4 observed, 2.93 expected, observed/expected ratio (o/e) 1.37, 90% interval 0.61 to 1.92.